TMEM202 (transmembrane protein 202)
Synonyms: FLJ27523
Tractability: Antibody: UniProt predicts a signal peptide or a membrane-spanning region; its Gene Ontology location is reachable by antibodies, with medium confidence.
Gene: Protein-coding gene on chromosome 15 (72,398,302 to 72,408,367, forward strand). Ensembl gene ENSG00000187806.
Subcellular location: Membrane
Gene Ontology:
Cellular component: plasma membrane; membrane
Genetic constraint (gnomAD): Loss-of-function variants: 26 observed, 27.42 expected, observed/expected ratio (o/e) 0.95, 90% interval 0.69 to 1.32. The upper end of that interval is the gene's LOEUF score, 1.32, which puts it in group 5 of 6, group 1 being the genes least tolerant of losing a copy. Missense variants: 301 observed, 345.64 expected, observed/expected ratio (o/e) 0.87, 90% interval 0.79 to 0.96. Synonymous variants: 122 observed, 125.29 expected, observed/expected ratio (o/e) 0.97, 90% interval 0.84 to 1.13.
Homologues: Orthologues: chimpanzee TMEM202 (96% identical), macaque TMEM202 (95% identical), pig TMEM202 (69% identical). Paralogues in human: GSG1 (17% identical), GSG1L (16% identical), GSG1L2 (15% identical), EMP1 (13% identical), PMP22 (13% identical), EMP2 (12% identical), LIM2 (12% identical), NKG7 (12% identical), CLDND2 (11% identical), EMP3 (8% identical).